CXCL12 (C-X-C motif chemokine ligand 12)
Diseases named in the same sentence as CXCL12 in open-access papers (continued):
Sharing a sentence is not in itself a finding about the gene and the disease.
colorectal cancer (continued). "For these studies, we took advantage of our unique colorectal carcinoma cells engineered to re-express CXCL12." (PMID 20877573, 2010). "Our data suggest re-establishment of CXCL12 expression in colorectal carcinomas potentially serves as a target to sensitize these cells to chemotherapies while limiting metastatic progression by modulating levels of Bcl-2 family members." (PMID 20877573, 2010). "Previously our laboratory has shown that CXCL12-expressing colorectal carcinoma cells are impaired in both their ability to form foci on soft-agar and actively metastasize." (PMID 20877573, 2010). "Herein, we show re-establishment of CXCL12 expression is a novel inducer of Bim and Bak in colorectal carcinoma cells and sensitizes these cells to anoikis." (PMID 20877573, 2010). "Subsequent work from our laboratory indicates that CXCL12 expression becomes silenced in both breast and colorectal carcinomas via DNA promoter hypermethylation and that this epigenetic repression enhances metastasis." (PMID 20877573, 2010). "Together these data suggest that constitutive CXCL12 expression and production inhibits tumor formation by sensitizing colorectal carcinoma cells to anoikis via upregulation of the Bim regulator." (PMID 20877573, 2010). "Previously we have shown re-establishment of CXCL12 expression in colorectal carcinoma cells inhibits metastasis by enhancing anoikis sensitivity." (PMID 20877573, 2010). "Conversely, our lab has previously shown that re-establishment of endogenous CXCL12 expression inhibits metastasis and sensitizes colorectal carcinoma cells to anoikis." (PMID 20877573, 2010). "Our previous studies have shown that autocrine CXCL12 reduces cellular colorectal carcinoma cell adherence compared to wild-type colonic carcinoma cells." (PMID 20877573, 2010). "Our earlier studies have shown that constitutive expression of the chemokine CXCL12 induces anoikis in colorectal carcinoma cells." (PMID 20877573, 2010). "This is important because epigenetic silencing of CXCL12 in human colorectal carcinoma cell lines has shown to promote and even enhance tumor metastasis in vitro and in vivo." (PMID 18001467, 2007). "In colorectal cancer, iCAFs enhance chemotherapeutic resistance by producing IL-6 and CXCL12." (PMID 41408647, 2025). "In colorectal cancer, IL-1RA reduces cancer cell metastatic potential by inhibiting the CXCL12/CXCR4 signalling axis, suggesting that it may have anti-metastatic effects in certain cancers." (PMID 40892159, 2025). "Meanwhile, it has been shown that CXCL12+ iCAFs are increased during colorectal cancer progression, and the pathway related to drug metabolism is activated in these cells, suggesting that CXCL12+ iCAFs are associated with chemotherapy resistance in patients with colorectal cancer." (PMID 39327633, 2024). "In addition, six homeostatic chemokines, CXCL12, CCL1, CCL20, CCL25, CCL27, and CXCL11, were upregulated in the peripheral blood of patients with advanced colorectal cancer, which has also been reported to be associated with tumor progression." (PMID 37063892, 2023). "Chemokine CXC motif receptor 4 (CXCR4) has long been thought to be the unique receptor for Chemokine CXC motif ligand 12 (CXCL12) and play important roles in chemotaxis, inflammation, cancer dissemination and organotropic liver metastasis of colorectal cancer (CRC)." (PMID 36210463, 2022). "In order to simulate the tumor microenvironment, we used a co-culture system composed of colorectal cancer cells or vascular endothelial cells and fibroblasts to detect the effects of stromal cell-derived CXCL12 on the invasion and migration of colorectal cancer and vascular endothelial cells." (PMID 34930323, 2021). "CXCL12 regulate metastatic potential of colorectal cancer was evaluated by proliferation, invasion and angiogenesis assays, respectively, in which invasion and angiogenesis assays used an in vitro system consisting of co-cultured colorectal cells and stromal cells." (PMID 34930323, 2021).
colorectal cancer (continued). "The 100 ng/mL of CXCL12 was significantly promoted the proliferation of colorectal cancer cells." (PMID 34930323, 2021). "CXCL12 derived from stromal cells in the tumor microenvironment depends on PI3K/Akt/mTOR signal to up-regulate the secretion of CXCL6 or down-regulate the expression of PTEN through PI3k/Akt signal to enhance the liver metastasis of colorectal cancer." (PMID 34930323, 2021). "In conclusion, IL-1α and CXCL12 are not only important molecules in the interaction between colorectal cancer cells and tumor microenvironment, but also important cytokines affecting liver metastass of colorectal cancer." (PMID 34930323, 2021). "Together, these results suggested that the autocrine IL-1α and paracrine CXCL12 co-enhances the metastatic potential of colorectal cancer cells; IL-1Ra can inhibit the metastatic potential of colorectal cancer cells via decrease IL-1α/CXCR4/CXCL12 signaling pathways." (PMID 34930323, 2021). "Additionally, ST3GAL6-AS1 was co-expressed with a variety of mRNAs, including PECAM1, VCAM1, CXCL12, CD34, CDH5, and VWF, and was associated with colorectal cancer progression." (PMID 33790949, 2021). "CXCL12 siRNA was transfected into colorectal cancer cells with small interfering RNA (siRNA)." (PMID 29305742, 2018). "Similarly, a recent study confirmed that CXCL12 was capable of promoting initiation of the transcription of Cd44 v6 in colorectal cancer stem cells by activating Wnt17." (PMID 29402989, 2018). "In colorectal cancer, CXCL12/CXCR4 axis could promote epithilial-mesenchymal transtion (EMT) and induce 5-fluorouracil (5-FU) resistance via up-regulating miR-125b-5p and enhancing autophagy." (PMID 28968424, 2017). "HIF-1α and CXCR4/CXCL12 have crucial roles in the metastatic process of colorectal cancer." (PMID 24629239, 2014). "We showed that re-expression of CXCL12 decreased the ability of breast and colorectal cancer cells to metastasize.Several studies haveextended those seminal findings to show beneficial effects of autocrine CXCL12 in breast, lung, gastric, and head and neck cancers." (PMID 24594697, 2014). "In addition to their roles in chemotaxis, CXCR4 and CXCL12 have been shown to regulate anoikis in breast and colorectal cancers." (PMID 24941119, 2014). "Therefore, we became interested in the role of the CXCR7/CXCL12 axis in the biologic processes of colorectal carcinoma." (PMID 22180778, 2011). "Similarly, Schimanski and colleagues found thatSW480, SW620, and HT-29 colorectal carcinoma cells expressed CXCR4 protein, asdid colorectal carcinoma tissue samples.CXCL12 induced the chemotaxis of SW480 and SW620 cells." (PMID 18779872, 2008). "This point is particularly interesting to note due to the fact that it has previously been shown in colorectal carcinoma that when endogenous sources of CXCL12 are epigenetically silenced, these cells more readily metastasize compared to those that engage in CXCR4/CXCL12 autocrine signaling." (PMID 18001467, 2007). "EMT and miR-125b are both simultaneously upregulated in human colorectal carcinoma (CRC) cells when the CXCR4/CXCL12 axis is activated." (PMID 37375460, 2023). "However, in another study with colorectal cancer patients, CXCL12 plasma levels were not related to A allele or GA / AA genotypes." (PMID 30227860, 2018). "We recently demonstrated in colorectal cancer that CXCL12 seems to be a decisive factor in the establishment of a pre-metastatic niche in the liver and interference with the CXCL12-CXCR4 axis may inhibit the pre-deposition of a distant organ to attract metastases." (PMID 29348861, 2017). "Given that CXCR4 and CXCL12 have been shown to have an additional role in anoikis in breast and colorectal cancers, future studies addressing the possible possibility that the upregulation of CXCR4 by AEG-1 may also function to regulate anoikis are of interest." (PMID 24941119, 2014).
colorectal cancer (continued). "These macrophages, in turn, secrete CXCL12, which increases cancer metastasis through the CXCL12/CXCR4/NF-κB signaling pathway, leading to colorectal cancer liver metastasis (CRLM)." (PMID 40034694, 2025). "Chemokines, including CXCL10, CXCL12, CX3CL1, CCL2, CCL5, CCL18, and CCL20, induce chemotaxis to promote cell migration and invasion in ovarian, lung, breast, and colorectal cancers." (PMID 38438872, 2024). "For instance, in prostate, non-small cell lung, and colorectal cancers, CAF-derived CXCL12 and CXCL14 facilitate the M2 polarization of macrophages." (PMID 38818409, 2024). "Previous studies have evaluated total protein or total mRNA expression of CXCL12 and its receptors CXCR4 and CXCR7 in stromal cells or colorectal cancer cells 32-34." (PMID 34976180, 2022). "The literature reported that CXCL12/CXCR4 axis was extensively involved in the migration and invasion of colorectal cancer and other cancers." (PMID 36569343, 2022). "For example, in colorectal cancer tissue, CXCL1, CXCL2, CXCL3, CXCL5, CXCL8, and CXCL11 were highly expressed, while CXCL12, CXCL13, and CXCL14 were little expressed." (PMID 36612163, 2022). "More and more evidence showed that the activation of CXCL12/CXCR4 axis is related to liver metastasis and poor prognosis of patients with colorectal cancer." (PMID 34930323, 2021). "And CXCR4 siRNA regulates the proliferation of colorectal cancer and vascular endothelial cells by inhibiting the CXCR4/CXCL12 axis." (PMID 34930323, 2021). "Autocrine IL-1α and paracrine CXCL12 co-enhances the metastatic potential of colorectal cancer cells; IL-1Ra can inhibit the metastatic potential of colorectal cancer cells via decrease IL-1α/CXCR4/CXCL12 signaling pathways." (PMID 34930323, 2021). "In colorectal cancer, senescent tumor cells inhibit CD8+ T cell infiltration by secreting a high concentration of CXCL12 and enhanced M2 macrophage differentiation by CSF1." (PMID 33643790, 2021). "CXCR4 antagonists potentiate ICI effect in HCC xenograft, in murine intraperitoneal papillary epithelial ovarian cancer and in murine colorectal cancer where NOX-A12, the CXCL12 antagonist L-RNA-aptamer, enhanced CD8 and NK infiltration." (PMID 31661001, 2019). "Recent studies showed that chemokine CXCL12 and its receptor CXCR4 play an important role in the proliferation and organ-specific metastasis of colorectal cancer." (PMID 29305742, 2018). "B7-H4 siRNA can effectively inhibit proliferation, invasion, and migration of LOVO cells by targeting CXCL12/CXCR4 and JAK2/STAT3 signaling, which can serve as a new target for colorectal carcinoma treatment." (PMID 26078947, 2015). "The CXC chemokine ligand 12 (CXCL12)/stromal cell-derived factor-1 (SDF-1) and CXC receptor 4 (CXCR4) axis is involved in human colorectal cancer (CRC) carcinogenesis and can promote the progression of CRC." (PMID 23098564, 2012). "Interestingly, in colorectal cancer (CRC), CXCL12 is also expressed most abundantly in endothelial cells, followed by fibroblasts." (PMID 36326956, 2023). "CXCL12 and its receptor CXCR4 are independent prognostic factors in colorectal cancer." (PMID 35615089, 2022). "For example, numerous preclinical studies have confirmed the efficacy of CAR-NK cells upon CXCL12/SDF-1α secreting glioblastoma and epithelial cell adhesion molecule (EpCAM) positive colorectal cancer cells in xenograft model by targeting EGFRvIII via intravenous infusion." (PMID 35303962, 2022). "Similar to CXCL12 signaling inhibition, blocking TGF-β signaling resulted in more T-cell infiltration and increased sensitivity to checkpoint inhibition therapy in multiple mouse models for breast cancer and colorectal cancer." (PMID 33466732, 2021). "The inhibition of CXCL12 or its receptor CXCR4 resulted in increased T-cell infiltration and rendered tumors vulnerable towards checkpoint inhibition therapy in mouse models for pancreatic and colorectal cancer." (PMID 33466732, 2021).
colorectal cancer (continued). "Our results suggest that IL-1Ra inhibits liver metastasis of colorectal cancer by inhibiting CXCL12, secreted by fibroblasts in colorectal microenvironment and blocking CXCR4/CXCL12 signal to enhance the proliferation, invasion and neovascularization of colorectal cancer cells." (PMID 34930323, 2021). "In conclusion, siRNA targeting of B7-H4 effectively suppressed the proliferation, invasion, and migration of LOVO cells by inhibiting the effect of CXCL12/CXCR4 and the phosphorylation of JAK2/STAT3 on increasing the metastatic potential of colorectal carcinoma." (PMID 26078947, 2015). "We found increased concentrations of CXCL12 in the peripheral blood of patients with advanced colorectal cancer (one-way ANOVA, CXCL12 control vs stage IV, p = 0.0014), suggesting a tendency for recruitment of B cells in the advanced stage of colorectal cancer." (PMID 37063892, 2023). "In colorectal cancer, elevated levels of systemic tissue inhibitors of metalloproteinases (TIMP) metallopeptidase inhibitor 1 (TIMP-1) trigger hepatic stellate cells to release chemokines, such as C-X-C motif chemokine 12 (CXCL12), that recruit neutrophils to the liver." (PMID 34202272, 2021). "And CXCL12 expression induced apoptosis specifically in nonadherent colorectal carcinoma cells." (PMID 24810923, 2014). "We hypothesize that maintaining focal adhesion protein expression, which is absent in CXCL12 cells regardless of Bim levels, is critical for further enabling metastasis of colorectal carcinomas expressing the chemokine." (PMID 20877573, 2010). "Having demonstrated Bim expression was upregulated in non-adherent colorectal carcinoma cells expressing CXCL12, we next examined whether RNAi-mediated repression of Bim would reverse anoikis sensitivity in those cells." (PMID 20877573, 2010). "Furthermore, inhibition of CXCL12 with the L-RNA-aptamer NOX-A12, which impedes CXCL12 interaction with CXCR4 and CXCR7, led to greater tumor infiltration by T and natural killer (NK) cells with an improved anti-PD1 therapy in a mouse model of colorectal cancer." (PMID 30420856, 2018). "Initial characterization of HT29 and HCT116 human colorectal carcinoma cells shows expression of both CXCR4 and CXCR7 chemokine receptors with no detectable CXCL12 expression." (PMID 20877573, 2010).
melanoma (124 papers, 2009 to 2026). A malignant, usually aggressive tumor composed of atypical, neoplastic melanocytes. "Direct expression of one or both factors has been observed in a wide range of tumors, and expression of CXCR4/CXCL12 has been associated with a poor prognosis in multiple cancers, including breast, ovarian, renal, lung, and melanoma." (PMID 36923305, 2022). "A recently described circRNA, circ_0020710, deriving from CD151 mRNA encoding an oncogenic transmembrane protein, promotes melanoma progression and contributes to melanoma immune evasion by sponging miR-370-3p and upregulating CXCL12 levels." (PMID 35159386, 2022). "Compared to controls, Ccr10 and Cxcl12/Cxcr4 levels were decreased in B16 melanoma tumors from Cbx3/HP1γ-deficient mice." (PMID 34721405, 2021). "Together, our data reveal an important role for A2BR in stimulating FGF2 and CXCL12 expression in melanoma-associated fibroblasts." (PMID 27590504, 2016). "Co-administration of A2BR antagonist PSB1115 completely reversed this effect, indicating a direct role for A2BR in inducing CXCL12 production in melanoma-associated fibroblasts." (PMID 27590504, 2016). "We determined that A2BR stimulation induces the expression of FGF2 and CXCL12 in melanoma-associated fibroblasts." (PMID 27590504, 2016). "Treatment of melanoma-associated fibroblasts with the A2BR agonist Bay60-6583 enhanced CXCL12 and FGF2 expression." (PMID 27590504, 2016). "Indeed, we confirmed that an increased i.t./stromal CXCL12 level was associated with therapeutic benefits in patients with melanoma undergoing anti–CTLA-4 immunotherapy." (PMID 35552271, 2022). "Moreover, increased hepatocyte CXCL12 expression is associated with increased CXCR4 (+) cells in melanoma and CRC liver metastasis presumably by promoting cancer cell invasion." (PMID 34298991, 2021). "The CXCL12 splice variant in melanoma had an intron loss, which argues for a functional activation." (PMID 34281234, 2021). "Similarly, the positive association of CXCL12 with cytotoxic T cell recruitment was related to the presence of DCs within melanoma." (PMID 30899263, 2019). "The expression of CXCL12 increased in melanoma-associated fibroblasts treated with Bay60-6583." (PMID 27590504, 2016). "CXCL12 and CXCL8 have been linked to immunotherapy unresponsiveness for colon cancer and melanoma patients." (PMID 38742117, 2024). "Its ligand, the CXCL12 chemokine, is present in many organs identified as common sites of melanoma metastasis." (PMID 38474372, 2024). "CXCL12 recruits suppressive immune cells to form an immune-inhibitory microenvironment, ultimately promoting the proliferation, migration and invasion of melanoma cells." (PMID 38762484, 2024). "Previous studies showed that the CXCL12/CXCR4 axis contributed to the formation of a pre‐metastatic niche for metastatic melanoma cells and metastasis development." (PMID 39496484, 2024). "In melanoma, circ_0020710 acts as a sponge for miR-370-3p and directly binds to it, which in turn upregulates CXCL12 expression." (PMID 38762484, 2024). "Elevated levels of CXCL12 are also found in dysplastic tissues, such as primary brain tumors, melanomas, and ovarian carcinomas." (PMID 37251376, 2023). "In 2006, Vianello and colleagues provided evidence that melanomas expressing elevated levels of CXCL12 can repel T cells, thereby abrogating Antigen (Ag)-specific T cell infiltration into the tumor and allowing it to escape immune control." (PMID 37251376, 2023). "Melanomas engineered to express low or high concentrations of CXCL12 display distinct levels of tumor infiltrating lymphocytes." (PMID 37251376, 2023). "In the resulting premetastatic niche consisting of VEGFR1+ progenitors, fibroblasts and fibronectin, expression of CXCL12 became highly expressed leading to the homing of CXCR4+ melanoma cells and metastasis." (PMID 37173970, 2023).